CAMTA2 (calmodulin binding transcription activator 2)
Description:
Transcription activator. May act as tumor suppressor.
Synonyms: KIAA0909
Tractability: PROTAC: ubiquitination databases record sites on it.
Gene: Protein-coding gene on chromosome 17 (4,967,992 to 4,987,684, reverse strand). Ensembl gene ENSG00000108509.
Subcellular location: Nucleus
Subcellular location (Human Protein Atlas): Nucleoplasm; Actin filaments; Cytosol; Mitochondria; Vesicles
Gene Ontology:
Molecular function: chromatin binding; histone deacetylase binding; protein binding; transcription coactivator activity; transcription coregulator activity; DNA binding; sequence-specific DNA binding
Biological process: cardiac muscle hypertrophy in response to stress; positive regulation of transcription by RNA polymerase II; regulation of transcription by RNA polymerase II
Cellular component: chromatin; nucleoplasm; nucleus
Genetic constraint (gnomAD): Loss-of-function variants: 54 observed, 132.3 expected, observed/expected ratio (o/e) 0.41, 90% interval 0.33 to 0.51. The upper end of that interval is the gene's LOEUF score, 0.51, which puts it in group 2 of 6, group 1 being the genes least tolerant of losing a copy. Missense variants: 1,327 observed, 1,573.4 expected, observed/expected ratio (o/e) 0.84, 90% interval 0.81 to 0.88. Synonymous variants: 582 observed, 618.06 expected, observed/expected ratio (o/e) 0.94, 90% interval 0.88 to 1.01.
Homologues: Orthologues: chimpanzee CAMTA2 (99% identical), macaque CAMTA2 (96% identical), pig CAMTA2 (95% identical), rabbit CAMTA2 (95% identical), rat Camta2 (92% identical), mouse Camta2 (92% identical), guinea pig CAMTA2 (91% identical), dog CAMTA2 (89% identical), tropical clawed frog camta2 (58% identical), zebrafish camta2 (7% identical). Paralogues in human: CAMTA1 (54% identical).
Diseases named in the same sentence as CAMTA2 in open-access papers:
CAMTA2 is named in the same sentence as 15 diseases in open-access papers, as found by Europe PMC text mining. Sharing a sentence is not in itself a finding about the gene and the disease. The quoted sentences say what the papers report.
cardiac hypertrophy (6 papers, 2012 to 2022). "CAMTA2 is expressed in cardiomyocytes, and is implicated in promoting cardiac growth: overexpressing CAMTA2 in the mouse heart leads to cardiac hypertrophy." (PMID 34499028, 2021). "Cardiac hypertrophy as a consequence transcriptional reprogramming of cardiac gene expression by CAMTA2 interaction with class II histone deacetylase has been reported." (PMID 29110692, 2017). "CAMTA2 shows expression after birth, is a potent co-activator of the cardiac specific transcription factor Nk×2.5, and is involved in cardiac hypertrophy." (PMID 22715383, 2012). "Camta2 has been shown to interact with Nkx2-5 and promote cardiac hypertrophy in mice." (PMID 24826987, 2014). "Meanwhile, CAMTA2 can also bind to NKX2-5 and participate in the pathogenesis of cardiac hypertrophy." (PMID 33195237, 2020). "CAMTA2, the only gene with a borderline significant p-value when comparing group-specific differential expression in reaction to LDIR (comparing N2+ and N0, crude model) has been shown to be involved in cancer, stress reaction across species, and cardiac hypertrophy." (PMID 36068491, 2022).
colon cancer (2 papers, 2020 to 2024). "Regarding the mechanism of miR-28-5p in the regulation of cancer cells, previous studies observed that miR-28-5p inhibited CAMTA2 expression and regulates colon cancer progression by suppressing Wnt/β-catenin signaling." (PMID 32566038, 2020). "Finally, we observed two ISRS model genes (CAMTA2 and FOXD1) with abundant research value in oncology, which have been proven as oncogenes in head and neck squamous cell carcinoma or colon cancer." (PMID 38512513, 2024).
colorectal tumors (1 paper, 2023). "As revealed by a contemporary research, CAMTA2 is significantly upregulated in many colorectal tumors and associates with poor survival." (PMID 38025193, 2023).
Dystonia (1 paper, 2017). An abnormally increased muscular tone that causes fixed abnormal postures. "Our study identifies a novel dystonia locus CAMTA2 that opens a new line of investigation associated with the role of CAMTA2 in the growth, differentiation, survival, and function of cells and their cellular mechanisms within the brain as related to movement disorders." (PMID 29110692, 2017). "In this study, we further delineate and genetically characterize the syndrome, identifying CAMTA2 as a novel candidate gene for a syndromic tremulous dystonia, and describe its clinical course and prognosis over a long follow-up period." (PMID 29110692, 2017).
heart failure (1 paper, 2025). Inability of the heart to pump blood at an adequate rate to meet tissue metabolic requirements. "These four genes CAMTA2, ITGB6, NFATc2, and XDH are all related to heart failure, fibrosis, and cardiovascular disease." (PMID 40181955, 2025).
myocarditis (1 paper, 2025). Myocarditis is a condition that is characterized by inflammation of the heart muscle (myocardium). "Myocarditis sera induced CAMTA2, ITGB6, NFATC2, and XDH gene expression significantly (p <0.05) above healthy sera." (PMID 40181955, 2025).
pancreatic cancer (1 paper, 2014). "AKT2 and MCM7 were overexpressed, and CAMTA2 and PFN1 were underexpressed in pancreatic cancer tissues than in morphologically normal operative margin tissues." (PMID 25502777, 2014).
cancer (3 papers, 2020 to 2024). A tumor composed of atypical neoplastic, often pleomorphic cells that invade other tissues. "Hence, we performed pan-cancer analysis to reveal the heterogeneity of CAMTA2 and FOXD1 expressions in tumor and normal samples across 33 tumor types." (PMID 38512513, 2024).
cardiovascular disease (2 papers, 2020 to 2025). "However, several studies have reported the role of CAMTA2 in cardiovascular diseases." (PMID 32649009, 2020).
tumor (2 papers, 2022 to 2024). "Further, CHGA, which plays a role in neuroendocrine secretion, BLRVB, a broad specificity oxidoreductase that is also involved in heme metabolism, and CAMTA2, which is possibly involved in cardiac growth and tumor suppression, were also all positively selected in pinnipeds but not in cetaceans." (PMID 35615068, 2022). "Secondly, since the characteristics of CAMTA2 and FOXD1 in NB remains unclear, more real-world researches enrolling more tumor specimens, as well as more experiments in vitro or in vivo should be carried out to explore their biological function in NB." (PMID 38512513, 2024).
CAMTA2 also shares sentences with these, for which no sentence is quoted: Autoimmunity (1 paper); cardiomyopathy (1); head and neck squamous cell carcinoma (1); infection (1); movement disorder (1).